THRA (thyroid hormone receptor alpha)
Diseases named in the same sentence as THRA in open-access papers (continued):
Sharing a sentence is not in itself a finding about the gene and the disease.
cancer (16 papers, 2011 to 2025). A tumor composed of atypical neoplastic, often pleomorphic cells that invade other tissues. "Dysregulation of THRA could be involved in cancer, as mutations in the ligand-binding domain and zinc finger domain of THRA were observed in HNSCC patients, though there was no change in level of expression." (PMID 36430573, 2022). "The shortage of THRα studies persuaded the tracing of TH effect on other tissues to understand THR behavior in cancer." (PMID 33846395, 2021). "While trends towards worse overall survival were observed in the triple negative and luminal A subtype cancers expressing high THRα and THRα1, this relationship was statistically significant only in the luminal A subtype for THRα1 (p = 0.04)." (PMID 30410118, 2018). "Studies have shown that THRA and THRB (another gene that encodes this receptor), may be involved in human cancer." (PMID 33767996, 2021). "Interestingly, the expression level of FOXJ3 was augmented in TSCC patients and previous reports of other cancer have suggested an oncogenic role of THRA." (PMID 33868377, 2021). "These opposing roles might explain previously observed and seemingly paradoxical roles of the THRα pathway in cancer development and progression." (PMID 30410118, 2018). "Interestingly, the augmented level of FOXJ3 in TSCC patients and previous reports on THRA in other cancers have suggested that these two factors may promote TSCC progression." (PMID 33868377, 2021). "Protein-level analyses in nine cancer types revealed decreased expression of PLCB4, SOD3, and THRA, alongside increased expression of HMGB2 and RAC2, relative to normal tissues." (PMID 40852729, 2025). "Of note, only a few studies have analyzed the molecular basis of THRA gene regulation, and none were performed in the context of cancer." (PMID 36217307, 2022). "The absence of an effect on cell survival with THRα or THRα1 knockdown is consistent with large scale functional genomic studies that demonstrate the gene is not essential in breast or other cancer cells." (PMID 30410118, 2018). "This site might be located between GRB7 and THRA, a gene located 315 kb from GRB7, given that 84 (97.7%) of the cancer specimens we assessed presented GRB7 amplification, whereas only 47 (54.7%) showed THRA amplification." (PMID 21288332, 2011). "With the exception of three clusters of NRs representing NR classes I (cluster I: RORC, VDR, PPARA, NR1D1, THRA, RORA, NR1H3; cluster II: RARB, PPARG, THRB) and III (cluster III: ESR1, PGR, AR, ESRRG), NR class was not a good determinate of NR expression patterns in the different cancer types." (PMID 32024906, 2020). "These experiments showed that the cytotoxic effect of dronedarone was independent of and not altered by THRα or THRα1 knockdown in all cell lines tested; this finding provides evidence to support that THRα or THRα1 is not the target that mediates dronedarone’s anti-cancer effects." (PMID 30410118, 2018).
genetic disorder (4 papers, 2014 to 2025). "Resistance to thyroid hormone (RTH) is a rare genetic disorder caused by mutations in the thyroid hormone receptors α or β (THRα, THRβ) genes, leading to impaired tissue responsiveness to thyroid hormones." (PMID 40761432, 2025). "A new genetic disorder has been identified that results from mutation of THRA, encoding thyroid hormone receptor α1 (TRα1)." (PMID 24914936, 2014).
adenocarcinoma (2 papers, 2021 to 2022). A common cancer characterized by the presence of malignant glandular cells. "We observed here that high CDX2 levels strongly upregulated the THRA promoter in all adenocarcinoma cell lines analyzed despite their different genetics and mutation statuses." (PMID 36217307, 2022). "Finally, in‐depth analysis of the Wnt pathway allowed us to recapitulate the regulation of THRA transcription and TRα1 expression by this signaling pathway in human adenocarcinoma cell lines as well as mouse enteroids." (PMID 36217307, 2022).
skeletal dysplasia (1 paper, 2014). Any Mendelian diseases that affects growth and development of the skeleton. "A six year-old girl with skeletal dysplasia and growth retardation was found to have a heterozygous THRA nonsense mutation resulting in expression of a truncated TRα1E403X protein." (PMID 24914936, 2014). "A second girl with similar thyroid function and skeletal dysplasia was found to have a heterozygous frameshift mutation in THRA resulting in expression of a truncated TRα1F397fs406X protein." (PMID 24914936, 2014).
THRA also shares sentences with these, for which no sentence is quoted: migraine (3 papers); autism (2); hepatocellular carcinoma (2); non-alcoholic steatohepatitis (2); -dependent (1); alopecia (1); Alzheimer disease (1); astrocytomas (1); autism spectrum disorder (1); brain cancer (1); cardiac hypertrophy (1); cerebral palsy (1); Cognitive impairment (1); developmental delay (1); dyslipidemia (1); Erythema (1); familial hypercholesterolemia (1); gastrointestinal tumors (1); gestational diabetes mellitus (1); glioma (1); Glucose intolerance (1); Hyperapobetalipoproteinemia (1); invasive ductal breast carcinoma (1); lipodystrophy (1); liver steatosis (1); lung squamous cell carcinoma (1); medulloblastoma (1); metastatic prostate carcinoma (1); mucinous carcinomas (1); neuroblastoma (1).
A further 10 diseases each share a sentence with THRA in 1 paper.